NIFKP9 (NIFK pseudogene 9)
Synonyms: MKI67IPP9
Gene: Processed pseudogene on chromosome 2 (127,170,011 to 127,170,231, forward strand). Ensembl gene ENSG00000237630.
Diseases named in the same sentence as NIFKP9 in open-access papers:
NIFKP9 is named in the same sentence as 1 disease in open-access papers, as found by Europe PMC text mining. Sharing a sentence is not in itself a finding about the gene and the disease.
NIFKP9 shares sentences with these, for which no sentence is quoted: dementia (1 paper).